BRAF (B-Raf proto-oncogene, serine/threonine kinase)
Diseases named in the same sentence as BRAF in open-access papers (continued):
Sharing a sentence is not in itself a finding about the gene and the disease.
lung adenocarcinoma (continued). "RAS and RAF oncogenes are amongst the best-characterised driver oncogenes and are mutated in a significant proportion of human cancers, notably pancreatic (∼90%) and lung adenocarcinoma (∼30%) in the case of KRAS, and melanomas (∼50%) and thyroid cancers (∼30%) in the case of BRAF." (PMID 26183450, 2015). "Here, we report a novel case of a middle-aged non-smoking female diagnosed with BRAF V600E and BRCA2 germline mutated lung adenocarcinoma, who had previously undergone a diverse array of cancer-targeted therapies, including PARP inhibitor, before the identification of the BRAF V600E mutation." (PMID 38715777, 2024). "Of the 11 patients with lung adenocarcinoma (LUAD), 6 (54.6%) had at least one actionable mutation, of which 3 (27.3%) were with EGFR mutations, 3 (27.3%) showed KRAS mutations, and none were with BRAF mutations." (PMID 37769655, 2023). "Finally, the TCGA lung adenocarcinoma (LUAD) database was consulted to study the expression of ACE2 in EGFR- and KRAS-mutant samples and ACE2 expression was correlated with EGFR/HER, RAS, BRAF, ROS1, ALK, and MET mRNA expression." (PMID 36077610, 2022). "We took into consideration different rare mutations observed in BRAF, PIK3CA, HER2, and NRAS detected with a total frequency equal to 16.7% of patients with lung adenocarcinoma harboring somatic mutations, which is not a negligible prevalence if transposed to the entire population." (PMID 32082488, 2020). "Interestingly, LCNECs harbor also alterations of oncogenes which are commonly found in lung adenocarcinomas, but usually absent in neuroendocrine tumors like SCLCs, such as RAF family genes, BRAF and NFE2L2 mutations." (PMID 30060526, 2018). "We extended study of epigenetic priming to a patient-derived xenograft (PDX) model of lung adenocarcinoma, LX7, which has poorly differentiated histology, is negative for KRAS, EGFR (exons 18–21), and BRAF mutations, and is negative for ALK-fusions by cytogenetic analysis." (PMID 25474141, 2015). "For lung adenocarcinoma, alterations in EGFR, KRAS, and BRAF were comparable between protocol patients and TCGA (data not shown)." (PMID 32914008, 2019).
metastatic disease (230 papers, 2006 to 2025). "In this report, we describe a rare case of BRAF V600E-mutated CRC with secondary metastatic disease concomitantly affecting the skin and parotid gland." (PMID 39935827, 2025). "The prevalence of BRAF mutations, paucity of effective clinical approaches, and poor prognosis made BRAF-mutant metastatic disease ideal for adoption of novel small molecules such as vemurafenib, selectively targeting the BRAFV600E oncoprotein." (PMID 39636745, 2025). "For metastatic disease harboring the BRAF V600E mutation, BRAF inhibitors are an available treatment; however, their utility as single-modality therapy is limited by near inevitable disease progression." (PMID 38275291, 2024). "Patients with BRAF or NF1 mutations were the only patients to present with brain metastases at the time metastatic disease was diagnosed." (PMID 38339344, 2024). "The novelty of our approach, aiming to evaluate BRAF mutation in primary and metastatic MMs, completes our preliminary communicated results, supporting the notion that BRAF mutation occurs most likely prior to the metastatic disease development." (PMID 38541077, 2024). "Trametinib is a MEK1/MEK2 inhibitor that was approved by the FDA in 2013 initially for patients with metastatic disease and a BRAF V600 mutation." (PMID 39272885, 2024). "BRAF mutations were harbored by (12%) 5/41 vs. (7.7%) 11/147 of the metastatic tumors with intact LKB1 expression." (PMID 38791897, 2024). "In this cohort, patients were only tested for the BRAF mutation when presenting with metastatic disease." (PMID 37240418, 2023). "A proportion of 100% of the patients with systemic metastatic disease tested positive for BRAF V600E mutation (4/4)." (PMID 38136349, 2023). "Patients with metastatic tumors undergo molecular testing for the BRAF V600 mutation to determine treatment options with BRAF/MEK inhibitors." (PMID 38003476, 2023). "BRAF mutations have mainly been studied in metastatic disease, in which a BRAF mutation was associated with worse prognosis." (PMID 37344790, 2023). "Overall survival (OS) was determined by the date of metastatic disease to date of death with stratification made based on factors including BRAF and RAS mutation status, age, and MMR protein loss type." (PMID 35274712, 2022). "Another phase 2 trial is enrolling BRAF V600E mutated patients NSCLC with metastatic disease; V600K or V600D mutated patients are considered for enrollment." (PMID 36230797, 2022). "One patient who had metastatic disease with BRAF V600E mutation was treated with only palliative chemotherapy as BRAF inhibitor was not feasible." (PMID 36200011, 2022). "BRAF mutations were higher in the primary tumor tissues than the metastatic tumor tissues in male and female patients." (PMID 35592200, 2022). "In our cohort, 185 patients with metastatic disease had predominantly mucosal melanoma, 20% had BRAF mutation, 11% KIT mutation and only one-third took any systemic treatment with a median PFS of 9 months, and one-third of them took an ICI agent." (PMID 35211204, 2021). "Out of 12 patients, five presented with BRAF V600E mutation in both the primary and metastatic tumors." (PMID 33716974, 2021). "The number of organs involved in metastatic disease and tumor load, the pattern of metastasis, left or right primary location and BRAF mutational status are known and well described prognostic factors in this population." (PMID 33238958, 2020). "The authors concluded that there is currently insufficient evidence to definitively state that KRAS wild-type/BRAF-mutated metastatic tumors respond differently to anti-EGFR therapy compared with KRAS wild-type/BRAF wild-type tumors." (PMID 32019056, 2020). "Vemurafenib, the first licensed targeted treatment for patients with metastatic disease and the BRAF V600E mutation, was also shown to increase short-term survival." (PMID 33409455, 2020).
metastatic disease (continued). "Consistency for BRAF mutations was 95.2% (V600E, V600K, and G469S variants) present in both the primary and metastatic tumors." (PMID 31455347, 2019). "KRAS mutational discordance between primary and paired metastatic tumors was identified in 2 patients (2/16, 13%), whilst BRAF mutation was concordant in the single patient with a BRAF mutant allele." (PMID 29423054, 2018). "In contrast with BRAF V600E mutation, metastatic tumors harboring rare mutations of BRAF codons 594 and 596 (less than 1% of CRCs) have been shown to have different prognosis and clinical outcome." (PMID 34532592, 2018). "The prognostic value of stratifying CC patients based on BRAF mutational status has been well reported, particularly in stage IV metastatic tumors, where patients with BRAFMT tumors have poor survival rates." (PMID 29568398, 2018). "Current research is focusing on both KRAS and BRAF as predictive and diagnostic biomarkers in patients with metastatic disease treated with anti-EGFR therapies, such as panitumumab and cetuximab." (PMID 28097409, 2017). "This resulted in the detection of a BRAF mutation in 125/230 samples (54.3%), including 46/88 (54.5%) primary tumors and 79/142 (55.6%) metastatic tumors." (PMID 23976959, 2013). "TOPK expression is an unfavourable prognostic indicator in sporadic patients with KRAS or BRAF mutations and also in patients with metastatic disease experiencing a response to anti-EGFR therapies." (PMID 19935791, 2010). "In conclusion, TOPK seems to be a valuable prognostic factor in patients with sporadic CRC with KRAS or BRAF gene mutations, as well as in patients with metastatic disease who respond to anti-EGFR therapies." (PMID 19935791, 2010). "Other genetic tests, such as BRAF mutation status, are only evaluated in metastatic tumors." (PMID 37629011, 2023). "Furthermore, we explore the ability to detect the circulating BRAF V600E hotspot mutation for longitudinal global disease monitoring in a subset of our cohort with multifocal metastatic disease." (PMID 33799709, 2021). "Interestingly, most patients with a BRAF mutation (N = 26, 76%) also exhibited synchronic metastatic disease." (PMID 31952366, 2020). "Alternatively, genetically heterogeneous metastatic tumors could derive from BRAF mutation-positive or BRAF WT primary tumor cells, leading to intrapatient discordance." (PMID 29148538, 2018). "All patients identified with BRAF mutations had metastatic disease." (PMID 28947956, 2017). "Additionally, BRAF mutations were associated with a poor prognosis in patients with metastatic disease." (PMID 27042173, 2016). "KRAS, NRAS, and BRAF mutations were always identical in both the primary and metastatic tumors." (PMID 25164765, 2014). "The lower BRAF mutation rate found in our study compared to the literature might be due to a selection bias since we screened only patients with metastatic disease." (PMID 24591764, 2014). "Pro-apoptotic agents 'Oblimersen', an antisense inhibitor of Bcl-2, and 'Sorafenib', an orally active small molecule inhibitor of wild type and mutant BRAF or PLX4032 a potent inhibitor of BRAF with the V600E mutation are at the forefront of novel therapies developed for advanced metastatic disease." (PMID 21682901, 2011). "Our results suggest that inhibition of TOPK could be beneficial for at least two groups of CRC patients together representing 30–40% of all cases, namely, those with a KRAS or BRAF mutation and those with metastatic disease supported by several factors." (PMID 19935791, 2010). "Notably, our genomic alteration in metastatic tumor data shows that KEAP1 mutations are enriched in BRAF Class 2 NSCLCs, suggesting that cooperation between Class 2 BRAF mutations and KEAP1 loss-of-function mutations may promote cancer progression." (PMID 38275886, 2024). "Thus, the consistency of BRAF mutations among primary and metastatic tumors is still being debated." (PMID 35328303, 2022).
metastatic disease (continued). "Metachronous dissemination was more frequently observed in ctRAS-low and ctRAS/BRAF wild-type profiles, whereas synchronous metastatic disease was significantly enriched in ctRAS-high and ctBRAF-mutant cases (p = 0.020)." (PMID 41515890, 2025). "The nomograms incorporated nine predictors: metastatic tumor count, cN stage, KRAS and BRAF mutation status, age, primary tumor location, neutrophil and platelet counts, and D-Dimer levels." (PMID 39991568, 2025). "The ensuing work-up revealed disseminated metastatic disease from the primary CRC, which was BRAF V600E-mutated (retrospective tissue analysis), affecting, besides the lungs, multiple uncommon sites, such as the skin and parotid gland." (PMID 39935827, 2025). "Conversely, BRAF-WT CMV+ patients presenting with metastatic disease were a mean 9.0 yr older than seronegative counterparts (95% CI, 3.0 to 13.0 yr; P = 1.3 × 10−4, Wilcoxon rank sum test)." (PMID 40269332, 2025). "Despite a lower incidence of BRAF V600 mutated CRC in Black patients, the mortality for this population remains high, as they tend to present with metastatic disease." (PMID 38275886, 2024). "Patients with BRAF and NF1 mutations appear to have the highest risk of brain metastases at the time of diagnosis of metastatic disease." (PMID 38339344, 2024). "Ten other patients subsequently developed metastatic disease during the 10-year follow-up period (two of whom were positive for BRAF V600E and two of whom were positive for NRAS Q61R)." (PMID 38183457, 2024). "Upon comparing the single gene analysis results and tumour progressive score between the primary and the resected metastatic tumour, we observed EGFR exon 19 deletion in the both tumour but BRAF V600E mutations only in metastatic tumour." (PMID 39139611, 2024). "A repeat scan 3 months after starting BRAF/MEK therapy demonstrated regression of her metastatic disease in the liver, spleen, and peritoneum, and decompression of her inferior vena cava with marked clinical and radiographic improvement." (PMID 39234402, 2024). "As its prognosis is, by far, worse in patients with unresectable metastatic disease than in those with locally limited resectable ones, clinical trials focusing on BRAF V600E CRC have been conducted for unresectable metastatic disease." (PMID 37605122, 2023). "Eligible patients require a pathologic diagnosis of CRC, have BRAF wild-type and microsatellite stable disease, and have 4 or fewer sites of metastatic disease identified on baseline imaging." (PMID 38196590, 2023). "Oncologists reported testing for KRAS, NRAS, BRAF, HER2, and mismatch repair deficiency/microsatellite instability in 72%, 65%, 63%, 56%, and 66% of patients with metastatic disease, respectively." (PMID 37682042, 2023). "For patients with metastatic disease, immune-checkpoint inhibitors and BRAF/MEK inhibitors remain valid therapeutic options, with superior overall response rates than conventional chemotherapy." (PMID 37892990, 2023). "At diagnosis of stage IV disease, NCCN recommends BRAF genotyping of either the primary or a metastatic tumor site as a predictive and prognostic marker for BRAF-targeted therapy." (PMID 36980565, 2023). "Even after adjusting for other factors such as BRAF status, treatment type and time to diagnosis of metastatic disease, the cutoff of ≥2 CTCs/7.5 mL remained a significant poor prognostic factor (p = 0.005)." (PMID 38201222, 2023). "The present study showed that even if BRAF-mutant metastatic disease is confined to one organ, the prognosis remains poor when the patient is treated with chemotherapy only." (PMID 35461290, 2022).
metastatic disease (continued). "The rates of v-Raf murine sarcoma viral oncogene homolog B (BRAF) and mismatch repair (MMR) gene mutations were higher in the primary tumor tissues than in the metastatic tumor tissues." (PMID 35592200, 2022). "In white patients, BRAF and MMR gene mutations were higher in the primary tumor tissue than in the metastatic tumor tissue." (PMID 35592200, 2022). "In the present multicenter cohort study, 292 patients with RAS/BRAF wild-type liver-limited metastatic disease starting from left-sided CRC were analyzed." (PMID 36428606, 2022). "For locally advanced tumors and metastatic diseases, targeted therapy such as BRAF inhibitors and MEK inhibitors shows therapeutic potential." (PMID 36059617, 2022). "In general, patients with BRAF-mut CRC have impaired survival not only in the metastatic setting but also in non-metastatic disease, as compared with patients with BRAF-wt CRC, and are resistant to chemotherapy." (PMID 35582524, 2022). "In the present multicentric cohort study, we explored the efficacy of a conversion strategy in a selected population of 272 left-sided RAS/BRAF wild-type CRC patients with liver-limited metastatic disease." (PMID 36428606, 2022). "In the present multicentric cohort study, we explored the efficacy of a conversion strategy in a selected population of left-sided RAS/BRAF wild-type CRC patients with liver-limited metastatic disease." (PMID 36428606, 2022). "Currently, the workup for metastatic disease recommends the investigation of activating mutations in KRAS (exon 2, 3, or 4) or NRAS (exon 2, 3 or 4) and BRAF (V600E), as well MMR status." (PMID 34201502, 2021). "Further, in two patients with metastatic disease and available longitudinal samples, we determine the BRAF V600E plasma levels by the ddPCR assay and correlate the findings with clinical status." (PMID 33799709, 2021). "This patient (subject #2) presented a BRAF H542Y mutation concomitant with an NRAS Q61R mutation in both the primary and the metastatic tumor in bone lesion." (PMID 33716974, 2021). "First exploratory effort few years before using avatar mice from pretreatment core biopsy samples of patients bearing BRAF V600-mutant metastatic disease mirrored the response of patients to selective BRAF and MEK inhibitors." (PMID 34090508, 2021). "The FDA approved a combination of dabrafenib (BRAF inhibitor) and trametinib (MEK inhibitor) to treat NSCLC patients with advanced or metastatic tumor carrying BRAF V600E mutation." (PMID 34834454, 2021). "We show that loss of KRAS and SMAD4 mutations characterizes the oligo-metastatic disease while a progressive mutational evolution (gain in KRAS, PI3KCA, BRAF and SMAD4) is observed in poly-metastatic evolving disease." (PMID 33096795, 2020). "Selective BRAF inhibitor therapy has yielded improvement in clinical outcome; however, genetic discordance between the primary lesion and the metastatic tumor has been shown to occur." (PMID 32313236, 2020). "In metastatic disease, the combination of BRAF-MEK inhibitors is applied in BRAF-mutated patients, while the therapeutic options in unmutated patients have by now been scarce." (PMID 31554169, 2019). "The apparent response of the patient's metastatic disease to trametinib suggests there is utility for treatment of BRAF fusion–positive tumors with MEK inhibitors, especially for those patients who have failed initial options." (PMID 31010895, 2019). "In the majority of multiple metastatic tumors, (BRAF:71.8%, NRAS:75%) metastases were relatively homogeneous regarding MAF." (PMID 31391014, 2019). "In patient 23, BRAF V600E mutant ctDNA was detectable 4 months prior to metastatic disease being clinically evident." (PMID 30719207, 2019).